COX7A2L (cytochrome c oxidase subunit 7A2 like)
Description:
Assembly factor that mediates the formation of some mitochondrial respiratory supercomplexes (respirasomes), thereby promoting oxidative phosphorylation and energy metabolism. Acts as a molecular adapter that associates with both mitochondrial respiratory complexes III (CIII) and IV (CIV), promoting their association. Mediates the formation of various mitochondrial respiratory supercomplexes, such as MCIII(2)IV(2), composed of two CIII and two CIV, and the CS-respirasome (MCI(1)III(2)IV(2)), composed of one CI, two CIII and two CIV. Not involved in the formation of the canonical respirasome (MCI(1)III(2)IV(1)), composed of one CI, two CIII and one CIV (By similarity). The formation of different respirasomes is important for cell adaptation to oxygen conditions and prevent metabolic exhaustion: supercomplexes mediated by COX7A2L/SCAF1 are required to maintain oxidative phosphorylation upon low oxygen conditions and promote metabolic rewiring toward glycolysis.
Synonyms: COX7AR; COX7RP; SCAF1; SCAFI; EB1; SIG81
Tractability: Antibody: UniProt predicts a signal peptide or a membrane-spanning region. PROTAC: ubiquitination databases record sites on it; its protein half-life has been measured.
Gene: Protein-coding gene on chromosome 2 (42,333,546 to 42,425,088, reverse strand). Ensembl gene ENSG00000115944.
Subcellular location: Mitochondrion inner membrane
Subcellular location (Human Protein Atlas): Mitochondria; Nucleoli
Pathways (Reactome):
Metabolism: Complex IV assembly; Respiratory electron transport
Cellular responses to stimuli: Cytoprotection by HMOX1
Gene Ontology:
Molecular function: protein-macromolecule adaptor activity; cytochrome-c oxidase activity
Biological process: mitochondrial respirasome assembly; mitochondrial electron transport, cytochrome c to oxygen; proton transmembrane transport
Cellular component: mitochondrial inner membrane; mitochondrion; mitochondrial membrane; respiratory chain complex IV
Genetic constraint (gnomAD): Loss-of-function variants: 18 observed, 14.69 expected, observed/expected ratio (o/e) 1.23, 90% interval 0.84 to 1.76. The upper end of that interval is the gene's LOEUF score, 1.76, which puts it in group 6 of 6, group 1 being the genes least tolerant of losing a copy. Missense variants: 179 observed, 146.8 expected, observed/expected ratio (o/e) 1.22, 90% interval 1.08 to 1.38. Synonymous variants: 65 observed, 61.34 expected, observed/expected ratio (o/e) 1.06, 90% interval 0.87 to 1.3.
Homologues: Orthologues: chimpanzee COX7A2L (100% identical), dog COX7A2L (89% identical), pig COX7A2L (89% identical), mouse Cox7a2l (89% identical), rat Cox7a2l (88% identical), guinea pig COX7A2L (86% identical), tropical clawed frog cox7a2l (74% identical), zebrafish cox7a2l (65% identical), Drosophila melanogaster COX7AL (23% identical), Drosophila melanogaster COX7AL2 (20% identical). Paralogues in human: COX7A2 (34% identical), COX7A1 (28% identical).
Diseases named in the same sentence as COX7A2L in open-access papers:
COX7A2L is named in the same sentence as 20 diseases in open-access papers, as found by Europe PMC text mining. Sharing a sentence is not in itself a finding about the gene and the disease. The quoted sentences say what the papers report.
breast carcinoma (9 papers, 2016 to 2025). "COX7A2L has also been associated with a range of cancers, including pancreatic, ovarian and breast cancer, with overexpression being a poor prognostic indicator." (PMID 40438247, 2025). "The role of COX7A2L (SCAF1) in promoting SC assembly has been demonstrated in breast cancer, pancreatic cancer, normal mouse tissue and bovine heart mitochondria." (PMID 35478774, 2022).
endometrial cancer (3 papers, 2019 to 2025). Primary or metastatic malignant neoplasm involving the endometrium (mucous membrane that lines the endometrial cavity). "Conversely, COX7A2L promotes glutamine metabolism and antioxidant defence by disrupting supercomplex assembly, and is more commonly linked to breast and endometrial cancers." (PMID 40596639, 2025). "Overexpression of COX7A2L might promote hypoxia tolerance in breastand endometrial cancer." (PMID 39070636, 2024). "Here we show that a stabilizing factor for mitochondrial supercomplex assembly, COX7RP/COX7A2L/SCAF1, is abundantly expressed in clinical breast and endometrial cancers." (PMID 31511525, 2019).
Alzheimer disease (2 papers, 2023). A progressive, neurodegenerative disease characterized by loss of function and death of nerve cells in several areas of the brain leading to loss of cognitive function such as memory and language. "Seven of these genes are Alzheimer’s disease-related, six are down-regulated with both Apoer2-ICDs (COX7A2L, FZD2, KIF5A, MAP2K2, PSENEN, RAF1) and one with only the Apoer2-ICD[Δ19] (SLC39A9)." (PMID 37461529, 2023).
acute kidney injury (1 paper, 2024). Sudden and sustained deterioration of the kidney function characterized by decreased glomerular filtration rate, increased serum creatinine or oliguria. "Since COX7A2L has not been reported in acute kidney injury, we chose it as a hub gene for further analysis." (PMID 39499704, 2024).
adrenocortical tumors (1 paper, 2024). "Among other DEPs, several have known roles in cancer (e.g. Dad1 and Brd9), adrenocortical tumors (Gnas), and cytochrome c oxidase subunits (e.g. Cox6c2 and Cox7a2l)." (PMID 38864697, 2024).
pancreatic ductal adenocarcinoma (1 paper, 2023). An infiltrating adenocarcinoma that arises from the epithelial cells of the pancreas. "Moreover, the physiological relevance of COX7A2L and mitochondrial supercomplex assembly in the regulation of glutaminolysis was highlighted, where the knockdown of COX7A2L promoted the proliferation of pancreatic ductal adenocarcinoma cells (PDAC) in a glutamine-dependent manner." (PMID 37351168, 2023).
cancer (6 papers, 2016 to 2025). A tumor composed of atypical neoplastic, often pleomorphic cells that invade other tissues. "Knockdown of COX7A2L reduces tumour growth in mice as well as proliferation in cancer cell lines, leading it to be proposed as an important therapeutic target." (PMID 40438247, 2025).
tumor (5 papers, 2016 to 2025). "Nonetheless, when considering genes that may encode novel therapeutic targets of both tumour insulin-expressing cell populations, the small number of genes ubiquitously expressed and upregulated in both clusters included COX7A2L (also known as COX7RP and SCAF1), with a mean 27-fold upregulation." (PMID 40438247, 2025). "In contrast, COX7A2L was one of a few genes ubiquitously expressed and significantly upregulated (> 20-fold) in both insulin-expressing tumour populations compared to other captured populations." (PMID 40438247, 2025).
COX7A2L also shares sentences with these, for which no sentence is quoted: breast tumor (1 paper); degenerative diseases (1); endometrial tumors (1); hepatocellular carcinoma (1); infection (1); Insulin resistance (1); ischemia (1); ischemia reperfusion injury (1); kidney injury (1); myocardial infarction (1); pancreatic cancer (1); triple-negative breast carcinoma (1).